KIT (KIT proto-oncogene, receptor tyrosine kinase)
Diseases named in the same sentence as KIT in open-access papers (continued):
Sharing a sentence is not in itself a finding about the gene and the disease.
melanoma (continued). "The aim of this study was to further elucidate c-KIT alterations in our well-characterised group of patients with mucosal melanomas that might support the role of c-KIT as a new therapeutic target in this subgroup of melanoma." (PMID 19018266, 2008). "Notably, KIT mutations were identified in 40% of acral melanoma cases, a subtype typically classified as “non-solar” melanoma, potentially associated with mechanical trauma rather than UV radiation." (PMID 41506188, 2026). "KIT mutations occur in approximately 9.5% of melanomas, with notable variation among subtypes." (PMID 40508177, 2025). "Together, these data suggest that broader-spectrum TKIs may provide benefit in select patients with KIT-altered melanoma, particularly those with resistance to first-line agents, though further investigation in larger, molecularly stratified cohorts is warranted." (PMID 41301010, 2025). "The literature suggests that malignant NCH may be distinct from melanoma based on the lack of GNAQ, NRAS, BRAF, and KIT mutations that are commonly identified in melanoma." (PMID 40265343, 2025). "Moreover, Artemisinin presented to have more advantage in melanoma therapy, because it could not only regulate c-KIT pathway, but also the complex regulatory networks in cancers as a multi-target drug." (PMID 39744440, 2025). "Furthermore, outcomes for melanoma with NRAS and KIT mutation receiving adjuvant immunotherapy remain unclear." (PMID 37403699, 2023). "Exploring lesser-known contributors to melanoma, such as c-KIT and JNK, may also be of interest." (PMID 36612301, 2023). "Moreover, further inhibitors are also available for melanoma harboring an amplified c-KIT gene." (PMID 38003476, 2023). "However, mucosal melanomas tend to differ from their cutaneous counterparts in terms of molecular profiling; albeit showing a heterogeneous molecular profile, they have lower BRAF and TERT, and relatively higher NRAS and KIT mutation frequencies." (PMID 35642348, 2023). "Given these clinical trial results demonstrating clinical benefit of KIT inhibitors, the National Comprehensive Cancer Network (NCCN) guidelines recommended KIT‐targeted therapy as one of the second‐line systemic therapies for metastatic or unresectable melanoma with active KIT mutations." (PMID 37403699, 2023). "However, the influence of KIT mutations on the efficacy of anti‐PD‐1 monotherapy in melanoma has not been extensively explored." (PMID 37403699, 2023). "Moreover, the downregulation of KIT signaling was detected in melanoma." (PMID 35563085, 2022). "The use of mTOR inhibitors as an alternative therapeutic strategy has demonstrated some success in KIT-activated melanoma, thereby suggesting that mTOR inhibitors as a monotherapy or in combination with first-line kinase inhibitors may be effective in targeting kinase-inhibitor-resistant tumors." (PMID 36551764, 2022). "The authors recommended that melanomas that originate on mucosal, acral, or chronic sun damage (CSD) skin should be investigated for KIT mutations and that imatinib is beneficial when tumors harbor KIT mutations, while it is ineffective when KIT is only amplified." (PMID 36407184, 2022). "Unfortunately, beyond BRAF, KIT mutations and tumor mutation burden, no clinically validated predictive markers exist in melanoma, although several promising biomarkers have been described, such as the expression of immune-related genes or mutations in the IFN-signaling pathway." (PMID 35628196, 2022). "In contrast to BRAF and NRAS, KIT mutations do not associate with histological subtypes or tumour stage; they do, however, have a close association with increasing age, acral mucosal subtypes of melanoma, and chronic sun-induced damaged sites." (PMID 36232957, 2022). "However, it remains to be demonstrated whether the rare c-KIT alterations are effective to tyrosine kinase inhibitors in malignant melanoma." (PMID 35720122, 2022). "Consequently, it contributes in what is known as KIT-derived melanoma." (PMID 36014478, 2022).
melanoma (continued). "As melanoma is characterized by activation of MAPK signaling due to mutations in BRAF, NRAS, NF1 and KIT genes, this suggests that further hyperactivation of MAPK signaling through loss of inhibitors of this signaling pathway may be deleterious to melanoma cells." (PMID 32767816, 2021). "There were no KIT mutations in any of the tested melanoma cell lines." (PMID 32767816, 2021). "Therefore, KIT has been suggested to be a potential therapeutic target for malignant melanoma." (PMID 34447613, 2021). "However, in CSD and non-CSD melanomas, we did not observe the previously reported difference in KIT mutation prevalence." (PMID 33648909, 2021). "Although not emphasized in previous publications, some mucosal melanomas may carry concomitant KIT/SF3B1 mutations." (PMID 34359736, 2021). "Our results supported the role of KIT mutations as an aggressiveness marker for melanoma patients and suggested that the development of the pathogenesis of KIT-mutated melanomas is independent of the common etiopathogenic pathways (nevus-proneness and chronic sun damage)." (PMID 33648909, 2021). "In light of the relatively high mutation rate of KIT in cutaneous melanoma and since BRAF, KIT, and NRAS mutations appear to be mutually exclusive, the screening of KIT mutations, at least in exons 9/11/13, is suggested in BRAF/NRAS double-wild-type melanoma patients." (PMID 34123788, 2021). "For instance, secondary A829P KIT mutation renders melanoma cells resistant to imatinib but has no influence on nilotinib and dasatinib, while the T670I KIT mutation exhibits resistance to imatinib, nilotinib as well as dasatinib, but can still be suppressed by sunitinib." (PMID 34350118, 2021). "However, none of the cases were found to harbor SF3B1 and KIT mutations in cutaneous melanomas, acral melanomas and melanomas of nasal cavity." (PMID 34102999, 2021). "Additionally, it has been discovered that C-KIT inhibitor imatinib harbors high efficacy against melanoma with KIT mutations, but not with KIT amplification only (54% vs 0% partial response)." (PMID 34350118, 2021). "Combinatorial therapies simultaneously targeting multiple pathways such as PI3K/MAPK, growth factors that may confer resistance, and immunotherapies should be explored in the setting of treating naïve c-KIT-mutant melanoma and patients with acquired resistance to c-KIT inhibitors." (PMID 33807778, 2021). "A pharmacodynamic study during a phase II clinical trial with nilotinib in KIT-altered melanoma showed a trend towards a reduction of growth factor expression in good responders compared to poor responders suggesting a link between growth factors and resistance to KIT inhibitors." (PMID 32344828, 2020). "Besides, KIT inhibition also showed efficacy in KIT-positive melanoma." (PMID 33109256, 2020). "However, instead, for others, such as NRAS or c-KIT mutated melanoma, the mutation’s predictive power is not sufficient to identify true responders’ subpopulations." (PMID 33233603, 2020). "In our skin melanoma cohort, similar to GIST, the most frequently mutated KIT exon is exon 11, although at lower frequency than in GIST (44.7%) followed by exon 9 (21.1%) and the other three exons (e13, e17, e18) with significant rates, suggesting a much broader carcinogenic targeting in melanoma." (PMID 31848942, 2020). "Moreover, most studies have focused on the effects of KIT on melanoma." (PMID 32015692, 2020). "Mechanisms of resistance to KIT inhibitors in melanoma remain unclear." (PMID 32344828, 2020). "Therefore, the combined inhibition of KIT with FGFR or MEK may be a next-step effective clinical strategy in KIT-mutant melanoma." (PMID 32344828, 2020). "Furthermore, we wanted to characterize the mutational pattern and hotspots of KIT in melanoma since the majority of studies did not provide a comprehensive picture." (PMID 31848942, 2020).
melanoma (continued). "Despite the clear capacity of small-molecule inhibitors to target and inhibit KIT mutants in melanoma cell lines in culture, only infrequent tumor responses of typically minimal durability have been observed in clinical trials treating KIT-mutant melanoma patients with KIT inhibitors." (PMID 32344828, 2020). "Consequently, we can assume that not all KIT mutations are drivers in melanomas and are not principal therapeutic targets." (PMID 31683701, 2019). "Thus, KIT mutations occur in up to 20% of mucosal melanomas, regardless of the location of the primary tumor." (PMID 29796159, 2018). "However, patients harboring c-KIT mutated melanoma did not uniformly respond to dasatinib in clinical trials." (PMID 30587121, 2018). "However, the prognostic importance of KIT mutations in melanoma was not evaluated in a series of adequate size." (PMID 29796159, 2018). "Additionally, we included BRAF, GNAQ and KIT mutant melanoma cells in our analyses." (PMID 30405888, 2018). "Melanoma patients with KIT D816H mutation, however, are not sensitive to imatinib." (PMID 28881731, 2017). "Likewise, imatinib therapy has also shown promising tumor responses in KIT-mutant melanomas." (PMID 28428884, 2017). "Many mucosal melanoma cells overexpress the cKit protein but only in some of these cells does activating mutation of the KIT oncogene occur; and some oral mucosal melanomas that express KIT mutations do not in fact overexpress the encoded protein." (PMID 28638859, 2017). "Similarly, MYSM1 was found at increased levels in c-KIT-positive melanoma." (PMID 28978033, 2017). "The lentiginous growth patterns of these lesions, the frequent genetic aberrations in KIT observed in such tumors, and the migratory advantage of KIT activated melanocytes are the rational that KIT pathway activation might confer an increased (intraepidermal) migratory phenotype of melanoma cells." (PMID 27322141, 2016). "Hence, based on our combined results we could demonstrate both in vitro and in vivo that acceleration of melanoma cell spread due to increased KIT activity could be arrested with specific kinase inhibitors." (PMID 27322141, 2016). "Since the patients that carry germline V559A and K642E mutations of KIT do not necessarily develop melanoma although some of them have hyperpigmentation, it can be concluded that these two mutations are not driver mutations in melanoma." (PMID 27777718, 2016). "However, treatment options remain limited for the patients that lack mutations in the five most commonly mutated melanoma genes (BRAF, NRAS, KIT, GNAQ and GNA11) and the prognosis of such patients is particularly pool with a median overall survival of less than 1 year." (PMID 26424083, 2015). "However, cell-free DNA analysis did not detect the KIT mutations found in the six positive melanoma samples, perhaps reflecting that these tumors although at advanced stage, did not release tumor DNA into the circulation or false-negative results." (PMID 26452027, 2015). "Although preliminary results in the literature suggest imatinib therapy may be helpful for the treatment of melanoma, this may not be the case for all patients with melanoma despite the presence of a KIT mutation." (PMID 25609545, 2014). "Besides, MAPK-independent molecules involved in the melanoma resistance mechanism include (i) upregulation of IGF-1R; (ii) PI3K/AKT signaling through the activation of c-KIT (a RTK also known as CD117); (iii) loss of PTEN through the suppression of BIM expression." (PMID 23533766, 2013). "Mutations in BRAF, c-KIT, and the ANR may be found in approximately 70% of all melanoma." (PMID 23476798, 2013). "Moreover, therapeutic phase II studies with the c-KIT blocker imatinib in unselected melanoma patients without known KIT mutation status were disappointing." (PMID 19018266, 2008).
melanoma (continued). "We could observe a significant higher immunohistochemical expression of c-KIT in mucosal melanomas that harbour a potentially activating KIT mutation as compared with tumours without KIT mutation." (PMID 19018266, 2008). "Thus, KIT mutations occur in up to 20% of mucosal melanomas irrespective of the location of the primary tumour." (PMID 19018266, 2008). "Thus, the minor subgroup of patients with mucosal melanomas and activating KIT mutations might be susceptible to therapeutic c-KIT blockade." (PMID 19018266, 2008). "Pharmacology-wise, rational strategies such as combining c-KIT and VEGFR inhibitors can suppress converging oncogenic pathways and mitigate resistance in advanced melanoma." (PMID 41394583, 2025). "One of the most pressing challenges in targeted melanoma therapy is the development of resistance to BRAF, MEK, and KIT inhibitors." (PMID 41302945, 2025). "In conclusion, our study revealed that actionable gene alterations in BRAF, NRAS, KIT, and NF1 are common in Japanese patients with melanomas." (PMID 39823560, 2025). "We further performed a series of rescued experiments to prove the regulatory relationship between c-KIT and PI3K/AKT in B16 melanoma cell line." (PMID 39744440, 2025). "In the present study, we, for the first time, found c-KIT as a new target of Artemisinin, and further confirmed Artemisinin's effect on regulating the KIT/PI3K/AKT pathway to inhibit the EMT signals and suppressing growth, migration, and invasion of melanoma." (PMID 39744440, 2025). "Currently there are multiple therapeutic targets in melanoma with inhibitors which include the MAPK pathway, MEC and KIT." (PMID 39741925, 2024). "All the canine and equine melanoma cell lines retained their wild-type status of BRAF exon 15 and 11, NRAS exon 3, and KIT exon 11 according to WES." (PMID 38397192, 2024). "CM has a high mutation load, and targeted therapy is an important therapeutic method for melanoma with driver gene alterations (i.e., BRAF, NRAS, and KIT)." (PMID 38229080, 2024). "The clinically characterized tumor molecular subtypes included BRAF, NRAS, KRAS, KIT, and PIK3CA mutant melanomas, with BRAF mutant melanomas being more prevalent in AYA compared to adult patients (77% vs 41%; Fisher’s exact test, P = 0.0003)." (PMID 38589406, 2024). "In view of the fact that the OFA includes some relevant genes in melanoma pathways apart from BRAF, such as NRAS, KIT, or MAP2K1, we embraced this panel to prospectively study a series of advanced melanoma patients." (PMID 39000050, 2024). "Key molecular markers include preferentially expressed antigen in melanoma (PRAME), c-Myc, and KIT (CD117)." (PMID 39766071, 2024). "We also report the different distributions of major oncogenic melanoma alterations (BRAF, NRAS, KIT) among different immune subtype groups." (PMID 38397409, 2024). "In melanoma treatment, Lenvatinib, an oral multiple tyrosine kinase inhibitor, has been employed to modulate VEGFR1-3, FGFR1-4, PDGFR, and KIT." (PMID 38791873, 2024). "Whereas, reflex NGS testing with an expanded panel also encompassing KRAS, KIT, and NRAS is only limited to ocular and mucosal melanomas." (PMID 39661469, 2024). "Here we used whole genome sequencing to genetically characterize the triple-wild-type melanoma (TWM), termed here as BRAF, RAS and KIT wild type, using the most common histological forms and excluding rare ones." (PMID 36980598, 2023). "The molecular classification of melanomas has practical consequences since the BRAF and KIT mutant forms can be treated by targeted therapies." (PMID 36980598, 2023). "Molecular testing for common melanoma driver genes, including BRAF, NRAS, KRAS, HRAS, NF1, and KIT, was available for this study." (PMID 37686691, 2023).
melanoma (continued). "Although raised from different cells, mastocytosis and melanoma share factors such as MITF, STAT3, and dependence on KIT signaling, suggesting some similarities in both pathologies." (PMID 36834926, 2023). "Considering the crucial roles of c-KIT in GIST and melanoma tumorigenesis, targeted inhibitors were thus used as the treatments for c-KIT-positive patients." (PMID 35720122, 2022). "Models with constitutive KIT activity, microcytic polycythemia, abnormal cecum morphology, development of GIST, melanoma or mastocytosis have been described." (PMID 36028522, 2022). "This review discusses several combination therapies that target melanoma biomarkers, such as BRAF, MEK, RAS, c-KIT, VEGFR, c-MET and PI3K." (PMID 35954441, 2022). "The most widely investigated c-KIT inhibitor was imatinib, which served as the first-line drug in GIST, whereas as an alternative treatment beyond immunotherapy in melanoma." (PMID 35720122, 2022). "Evaluation of combination therapies using KIT inhibitors and STAT inhibitors for treatment of melanoma is thus far minimally studied and therefore demands further consideration." (PMID 35954441, 2022). "Several clinical trials are testing novel TKIs and combinations of TKIs with other systemic therapies for melanomas, such as NCT02071940, which involves evaluating PLX3397 (plexidartinib, a multi-target TKI) in advanced KIT mutant acral and mucosal melanomas." (PMID 34831002, 2021). "Consistent with this idea, we noted that KIT gene localization was similar in NTF2 high dox + cells and VGP primary melanoma cells." (PMID 34880267, 2021). "In the present study, the expression of KIT and VWF in the melanoma metastasis samples significantly increased." (PMID 34582363, 2021). "Furthermore, we showed that most KIT mutated melanomas seemed not to follow a nevogenic development pathway either, given the lower number of nevi in melanoma patients with KIT mutated melanomas and that none of the nevus-associated melanomas presented KIT mutations." (PMID 33648909, 2021). "Future studies should explore the discrepancy in response rates between c-KIT inhibition in c-KIT-mutant GIST and melanoma." (PMID 33807778, 2021). "There are already several different drugs that are available for the extraocular melanomas, such as BRAF inhibitors and c-KIT inhibitors, and it is possible repurpose them to treat CM." (PMID 34681018, 2021). "Using a human kinome siRNA screen, LMTK3 was identified to have a role as a novel KIT regulator in KIT-mutant GIST and melanoma cells." (PMID 34582708, 2021). "The results of the survival analysis of patients with melanoma in TCGA demonstrated that the high expression of CDK2, CDK4, KIT, and VWF significantly reduced the survival rate of patients." (PMID 34582363, 2021). "Specifically, genes upregulated or downregulated in response to UV radiation involve CDKN1C, CDK2, COL11A1, KIT, and IGF1R, the majority of which are identified as differentially upregulated in melanoma versus atypical tumor or nevus." (PMID 35052351, 2021). "It has also been shown to have activity against both c-KIT and FGF2, and it has demonstrated promise in treating c-KIT-mutant melanoma, warranting further study." (PMID 33807778, 2021).